RN7SKP196 (RN7SK pseudogene 196)
Gene: Miscellaneous RNA gene on chromosome 10 (58,869,184 to 58,869,528, forward strand). Ensembl gene ENSG00000252076.
Homologues: Orthologues: chimpanzee 7SK (99% identical), guinea pig 7SK (38% identical), mouse Gm56391 (37% identical). Paralogues in human: RN7SKP124 (53% identical), RN7SKP3 (53% identical), RN7SKP79 (53% identical), RN7SKP133 (52% identical), RN7SKP250 (52% identical), RN7SKP77 (52% identical), RN7SKP225 (51% identical), RN7SKP78 (51% identical), 7SK (50% identical), RN7SKP127 (50% identical), RN7SKP204 (50% identical), RN7SKP120 (50% identical), and 283 more.